ALB (albumin)
Diseases named in the same sentence as ALB in open-access papers (continued):
Sharing a sentence is not in itself a finding about the gene and the disease.
liver dysfunction (continued). "Liver dysfunction was detected in two patients (cases 3 and 4), including abnormally low plasma albumin levels and abnormally elevated alanine aminotransferase and aspartate aminotransferase levels." (PMID 36211956, 2022). "Risk factors for liver dysfunction were high baseline IL6, albumin, and total bilirubin, and mALBI grade as found in univariate analysis." (PMID 34080071, 2021). "Other possible surrogate markers for liver dysfunction, such as low serum albumin, high/low transaminases, and low cholinesterase were also not significantly correlated in this study." (PMID 34830830, 2021). "Enzymatic activities of the liver function enzymes (ALT, AST), total protein and albumin were used in this study to evaluate liver dysfunction." (PMID 32637701, 2020). "Based on laboratory parameters such as albumin, bilirubin, and transaminases, virtually all patients had liver dysfunction or damage, while 32 patients presented with bleeding complications or disseminated intravascular coagulation (DIC)." (PMID 32076823, 2020). "The results of albumin and bilirubin can be readily obtained as a routine blood test, so both scores are completely objective measures of liver dysfunction." (PMID 30917853, 2019). "Total protein was reduced, albumin, which is produced by the liver and decreased in liver dysfunction, was increased for animals at TZO verses PL." (PMID 30581572, 2018). "Regarding markers of liver dysfunction, we observed a significant increase in the albumin/globulin ratio (p = 0.012), particularly at a dose of 100 mg DINCH/kg/day (1.21 ± 0.03, p < 0.01, n = 16), compared with controls (1.07 ± 0.02, n = 16)." (PMID 28894178, 2017). "Decreased levels of total protein and albumin as recorded in paracetamol-treated rats revealed the severity of hepatopathy." (PMID 28265544, 2017). "Nevertheless, the use of urinary metabolites is a non-invasive method and we controlled for albumin as marker for liver function and also liver dysfunction in all analyses." (PMID 29017568, 2017). "The low serum albumin concentration was always accompanied by liver dysfunction and poor protein concentrations." (PMID 27103467, 2016). "Care and correction of liver dysfunction and its comorbidities, like lower serum albumin and sodium, should be incorporated into the treatment strategy for portal cavernoma." (PMID 26949386, 2016). "In bilirubin levels, the administration of the two apitherapy formulations to the groups with experimental induced hepatopathy improves the bilirubin levels, that are albumin dependent." (PMID 25178061, 2014). "Clinical data analysis showed liver dysfunction (decreased albumin), immune system activation (increased globulin), and complement system activation (increased C4, C3) in PTB patients." (PMID 24484408, 2014). "Most (69%) had >25% of the liver volume effected by tumor and/or pre-existing liver dysfunction (41% albumin <35 g/L; 14% total bilirubin >1.2 mg/dL); 7 (24%) had received prior liver-directed therapy (resection, RFA, TACE or 131I-lipiodol)." (PMID 24614178, 2014). "Often critically ill patients have lower albumin, liver dysfunction and therefore lower vitamin D binding protein, which is associated with lower 25(OH) D levels that are still considered to be normal when free levels are normal." (PMID 24661739, 2014). "The severity of liver dysfunction was evaluated by either Child-Pugh classification or serum albumin level." (PMID 23776499, 2013). "Albumin–bilirubin (ALBI) score was calculated as the marker of liver dysfunction." (PMID 41153732, 2025). "Additionally, a high international normalized ratio correlated with lower albumin levels, a marker of liver dysfunction and poor nutritional status." (PMID 40332145, 2025). "Lower albumin levels in Group 2 reflect advanced liver dysfunction and impaired synthetic function." (PMID 40943916, 2025).
liver dysfunction (continued). "However, albumin levels can be influenced by various factors such as liver dysfunction and chronic inflammation, which limit the predictive value of albumin alone." (PMID 40667438, 2025). "The study findings also highlighted that decreased albumin levels signal early liver dysfunction." (PMID 40954485, 2025). "This decline in LDM-2 may be attributed to infection-induced liver dysfunction and an increased production of acute-phase proteins, which suppress hepatic albumin synthesis." (PMID 40357039, 2025). "The ligands used for the SEB test were carefully selected based on their binding sites to albumin in order to cover the most important albumin modifications that may occur in liver dysfunctions." (PMID 38228668, 2024). "Considering this, it is not surprising that in the sub-analysis of the CHARM study, after adjustment for confounding factors, albumin has lost its prognostic role during a median follow-up of 3.2 years, in fact in the multivariate model also parameters of liver dysfunction were included." (PMID 38776047, 2024). "Since HSA is continuously and exclusively synthesized and matured in the liver, albumin modifications may be directly related to the chemical environment into the hepatocytes, hence any liver dysfunction." (PMID 38228668, 2024). "The association of albumin and AKI has been discussed mainly in patients with liver dysfunction." (PMID 37009616, 2023). "In accordance with our results, decreased serum albumin as a drawback of neuroinflammatory AD-type progression may results in server liver dysfunctions due to systemic malnutrition inflammatory syndrome." (PMID 37017850, 2023). "There was dose-dependent liver dysfunction with bilirubin elevation and albumin decrease." (PMID 35110610, 2022). "Second, platelet counts and serum albumin levels could be influenced by other factors such as coagulation disorder and liver dysfunction, which might affect the predictive accuracy of prognosis." (PMID 35241740, 2022). "In this analysis, the three significant variables are risk factors for DIC in septic patients, with an odds ratio of 2.363 for low albumin representing liver dysfunction, 2.414 for respiratory infection, and 2.181 for receiving antibiotic treatment after 1 h or longer." (PMID 36362708, 2022). "Similarly, there was a dose-dependent liver dysfunction with bilirubin elevation and albumin decrease." (PMID 35110610, 2022). "Compared with albumin, prealbumin is more sensitive to protein malnutrition and liver dysfunction." (PMID 35962373, 2022). "ADAMTS13 antigen levels were also reduced and >80% of patients with ADAMTS13 activity levels <30% had albumin levels below normal reference range, thus liver dysfunction may explain a low ADAMTS13 activity in these patients." (PMID 33709050, 2021). "Specifically, low levels of albumin and urea indicate liver dysfunction." (PMID 34065411, 2021). "And in the HCC patients who underwent liver resection, the lower albumin level means the HCCs may have had liver dysfunction even liver failure which had high mortality rate and worse clinical outcomes." (PMID 32026332, 2021). "Furthermore, markers of liver dysfunction (albumin, total bilirubin, and INR) and inflammation (IL-6) were also associated with elevated levels of MGO." (PMID 34654829, 2021). "Therefore, we can’t calculate the Child-Pugh scores and albumin-bilirubin (ALBI) grade to evaluate the severity of liver dysfunction and the treatment situation of T2DM." (PMID 33315940, 2020). "Multivariate linear regression analysis revealed that circulating CLU levels were negatively associated with outcome parameters indicating jaundice status, degree of fibrosis, and liver dysfunction, but positively correlated with serum albumin and platelet number of BA patients." (PMID 33184463, 2020). "Changes in serum total protein values may indicate liver dysfunction as the liver is the main site of plasma proteins synthesis, primarily albumin." (PMID 30669347, 2019).
liver dysfunction (continued). "Lastly, the relationship between CRP/ALB ratio and liver dysfunction could be an important issue for prognosis in postoperative ICU patients in our study." (PMID 29495423, 2018). "Our findings though differ from the CRYCO study, which showed a significant increase in risk of mortality associated with hyperoncotic albumin without risk of liver dysfunction after covariate adjustment." (PMID 30564306, 2018). "This might be primarily due to worse liver dysfunction in patients admitted on off-hours, such as lower albumin and higher prothrombin time, INR, Child-Pugh score, and ALBI score." (PMID 30631756, 2018). "The liver dysfunction, will accompanied with albumin decrease in blood." (PMID 29254185, 2017). "A number of biomarkers of liver dysfunction have been indicated as prognostic in advanced cancer including: serum vitamin B12, albumin, bilirubin, aspartate aminotransferase (AST), ALT, ALP, gamma-glutamyl transferase (GGT), international normalised ratio (INR), LDH and cholesterol." (PMID 28384249, 2017). "This was consistent with the fact that a declined ALB level could reflect liver dysfunction as ALB was synthesized in the liver." (PMID 26057656, 2015). "The decrease in total protein and albumin in Cyp-treated rats may be due to the liver dysfunctions and disturbance in the biosynthesis of protein." (PMID 26265923, 2015). "We report here a new case diagnosed in a 45 years old man of Southwestern Asian origin, living in Switzerland, on the basis of his low ALB concentration (0.9 g/L) in the absence of renal or gastrointestinal protein loss, or liver dysfunction." (PMID 22174600, 2011). "Abnormal glucose and albumin concentrations could also indicate liver dysfunction in this group." (PMID 41302543, 2025). "Furthermore, the predictive performance of LAR for hospital mortality remained good in both sensitivity analyses, with AUC values similar to the primary analysis (AUC 0.845, 95% CI 0.814–0.873 after excluding albumin substitution; AUC 0.810, 95% CI 0.774–0.843 after excluding liver dysfunction)." (PMID 40748973, 2025). "Low albumin levels in the blood of cows may also indicate liver dysfunction." (PMID 38396578, 2024). "However, due to the major role of the liver in endobiotic and xenobiotic drug metabolism, coagulation, albumin, and production of acute phase reactants, liver dysfunction may affect the pathophysiology of the COVID‐19 disease." (PMID 36254683, 2022). "Therefore, the decreased level of albumin might indicate severe degree of cytokine storm and organ damage including liver dysfunction in COVID‐19 patients." (PMID 32914892, 2020). "Liver dysfunction could impact albumin production in SCD patients." (PMID 32776978, 2020). "Decreased levels of total protein and albumin as recorded in paracetamol-treated rats revealed the severity of hepatopathy and may be attributed to the damage produced and localized in the endoplasmic reticulum leading to decrease in protein synthesis (Kanchana and Sadiq, 2010 ▶)." (PMID 27222838, 2016). "Lower serum albumin may also indicate some conditions other than liver dysfunction." (PMID 23947772, 2013). "Concurrent declines in hepatic synthetic markers—albumin (Δ = −0.82 g/dL) and prealbumin (Δ = −2.74 mg/L)—mirror patterns observed in NAFLD progression, suggesting MetS exacerbates subclinical liver dysfunction." (PMID 41170367, 2025). "Elevated bicarbonate (45.2 mmol/L) and metabolic alkalosis also exist, accompanied by liver dysfunctions (elevated AST and low albumin)." (PMID 40625516, 2025). "Patients with ferritin > 390 ng/mL had a higher systemic inflammation level (WBC, NEUT%), liver dysfunction (ALT, AST, TBIL, LDH, ALB), iron metabolism disorders (TF, TIBC) and partly biochemical dysfunction (BUN)." (PMID 41280746, 2025).
liver dysfunction (continued). "This consistent pattern across diverse populations suggests that albumin may serve as a sensitive biomarker for monitoring chronic pesticide exposure, potentially detecting subclinical hepatic effects before conventional markers indicate severe liver dysfunction." (PMID 40427884, 2025). "Biochemical analyses confirmed progressive liver dysfunction, as indicated by significant elevations in liver enzymes (AST, ALT, and ALP), bilirubin levels, and GGT, along with decreased albumin levels in later stages of cholestasis." (PMID 41170193, 2025). "Albumin, a protein synthesized by the liver, is often low in patients with MAFLD and thus indicates early liver dysfunction, indicating impaired liver synthetic function." (PMID 40954485, 2025). "In conclusion, males with KS have a mild liver dysfunction, reflected by a significant increase in ALAT, alkaline phosphatase, PP and decreased levels of albumin, compared to an age matched control group." (PMID 38816662, 2024). "UV analyses determined several significant factors contributing to survival: ECOG PS, serum albumin, AFP levels, switching to sorafenib, advanced stage BCLC C, liver dysfunction (CTP C), tumor progression, and disease progression." (PMID 39609726, 2024). "Similar to these reports, our study found that pregnant women of NHB newborns indeed show significant liver dysfunction such as high levels of ALT, AST, ALT/AST and TBA, and low ALB level." (PMID 38172739, 2024). "Noninvasive models such as the model for end-stage liver disease (MELD), albumin-bilirubin (ALBI) grade and easy (EZ)-ALBI grade, platelet-albumin-bilirubin (PALBI) and platelet-albumin (PAL) are used to evaluate liver dysfunction." (PMID 37046586, 2023). "The albumin–bilirubin (ALBI), easy (EZ)-ALBI, platelet-albumin–bilirubin (PALBI), platelet–albumin (PAL) score, and MELD 3.0 score are used to evaluate the severity of liver dysfunction." (PMID 38069310, 2023). "The albumin-bilirubin (ALBI) grade and EZ (easy)-ALBI grade are used to indicate the severity of liver dysfunction in HCC, but the predictive accuracy of these two models in HCC patients with ascites is unclear." (PMID 36765711, 2023). "More recently, the albumin–bilirubin (ALBI) grade—a simple and objective method based solely on serum levels of albumin and bilirubin—was proposed to evaluate liver dysfunction, and has been validated by several research groups." (PMID 35158917, 2022). "Liver function test further revealed that M1-BMDM infusion significantly elevated the levels of ALT and TBIL and reduced the levels of ALB, indicating M1-BMDM infusion aggravated post-hepatectomy liver dysfunction." (PMID 33771984, 2021). "Hepatopathy patients revealed significantly altered parameters for cardiac function (proBNP), liver synthesis (GLDH, INR, and albumin) and cholestasis (bilirubin, gGT)." (PMID 33765046, 2021). "As in previous studies, indicators of the severity of hemorrhage (hemoglobin) and severity of liver dysfunction (MELD score, albumin, and bilirubin) were prognostic factors for cirrhotic patients with variceal bleeding." (PMID 32508912, 2020). "A decreased level of albumin, as recorded in APAP-administered rats, revealed the severity of hepatopathy." (PMID 31049130, 2019). "The ALBI score, a newly prognostic tool involving only two common laboratory parameters of albumin and bilirubin, was initially applied in patients with HCC for assessing the severity of liver dysfunction." (PMID 30540824, 2018). "Most of the patients suffered from liver dysfunction and exhibited elevated ALT, AST, total bilirubin (TB), direct bilirubin (DB), alkaline phosphatase (ALP), and GGT levels, as well as decreased albumin levels." (PMID 29851797, 2018). "The levels of aminotransferases and other liver function tests (AST, ALT, γ-GT, AP, albumin INR, platelet count, cholesterol, HDL, LDL) reflected the expected liver injury and liver dysfunction." (PMID 29346443, 2018).
liver dysfunction (continued). "Fourth, liver dysfunction, represented by elevated AST levels, may impair the synthesis of both RBP4 and albumin, further exacerbating the decline in nutritional and inflammatory balance." (PMID 40881125, 2025). "Albumin is a type of negative acute-phase protein, meaning its levels drop quickly when the body is dealing with an infection, under stress, or experiencing liver dysfunction." (PMID 41204601, 2025). "However, serum albumin concentrations were significantly lower in the PC group compared to the NC and CAT-only groups, further indicating liver dysfunction." (PMID 40937199, 2025). "Highlighting the significance of liver scoring systems, including the Child-Pugh score, end-stage liver disease, albumin-bilirubin (ALBI) score, and fibrosis-4 (FIB-4) index, the study explores their role in assessing liver dysfunction severity and predicting outcomes." (PMID 38681340, 2024). "It should be recognized that the liver dysfunction is not the only way for albumin and bilirubin to be changed by trauma." (PMID 38721021, 2024). "Interestingly, there were moderate correlations between fT3 and parameters of liver dysfunction (MELD: ρ = -0.448; p <0.001; and albumin: ρ = 0.434; p <0.001) and systemic inflammation (IL-6: ρ = -0.496; p <0.001; and CRP: ρ = -0.356; p <0.001)." (PMID 38125301, 2024). "Reduction in serum albumin, proteins, and globulin in BPF-treated fish may be because of kidney and liver dysfunctions." (PMID 39555222, 2024). "Fourth, liver-related decompensation and relevant medications were used as indicators of liver dysfunction; however, Child–Pugh and albumin–bilirubin scores were not available." (PMID 38067235, 2023). "A routine assessment of hepatic coagulation parameters (including antithrombin III)—likely a more sensitive indicator of acute liver dysfunction than albumin—in this patient cohort prior to conditioning did not reveal significant abnormalities." (PMID 38276491, 2023). "Similarly, abnormal blood urea nitrogen (BUN) and albumin (ALB), which usually means that the patient has renal damage and liver dysfunction, respectively, affect the survival time of the patient." (PMID 35812398, 2022). "The changes in serum albumin were not correlated with other markers for liver dysfunction (AST, ALT and GGT) at 3 and 6 months after the start of pemafibrate." (PMID 35203610, 2022). "Lactate metabolism and albumin levels may influence serum LDH and GA levels due to liver dysfunction; thus, we analyzed serum GPT levels to verify the measurements for all the patients who did not have liver dysfunction." (PMID 36589820, 2022). "Serum levels of transaminases, albumin (liver dysfunction), and urea (renal toxicity) were not elevated in mice that received high doses of siMCJ compared with control mice." (PMID 32620763, 2020). "Serum albumin level, a widely used evaluation indicator of liver dysfunction, was not measured in most patients in our study, and therefore, was not included as a variable." (PMID 33272195, 2020). "The correlations of lipid profile indicators (triglyceride, cholesterol, HDL-C and LDL-C) with liver function biomarkers (INR, bilirubin, albumin, CRP, platelet, AST/ALT ratio) and liver dysfunction scoring results (CTP score and MELD score) were assessed by Pearson χ2 test." (PMID 30927926, 2019). "Our analysis identified the occurrence of cerebral, respiratory, and circulatory failures during admission, and severe liver dysfunction defined by the baseline parameter of prolonged INR, high bilirubin, and low albumin levels as important factors in determining the prognosis of ACLF patients." (PMID 31291342, 2019). "Since albumin is produced in the liver, a decreased in albumin levels in an adult male with no other identifiable basis for this finding is used as a surrogate for liver dysfunction." (PMID 29147378, 2014).